FUCA1 (alpha-L-fucosidase 1)
Diseases named in the same sentence as FUCA1 in open-access papers (continued):
Sharing a sentence is not in itself a finding about the gene and the disease.
tumor (21 papers, 2013 to 2025). "Lower FUCA1 expression levels were associated with advanced-stage tumor formation with inferior survival outcomes, especially in TNBC patients." (PMID 26204487, 2015). "The significant upregulation of MX2 in high-risk patients, along with the reduced expression of FAM50B, FUCA1, AKAP6, and FCER1A in this group, further supports their potential roles in tumour progression and immune regulation." (PMID 40329678, 2025). "The observation that expression of FUCA1 inhibits the EGFR pathway, implicated in promoting cancer, again supports the potential role of FUCA1 as a tumor suppressor." (PMID 39123480, 2024). "Down-regulation of FUCA1 can enhance autophagy and inhibit macrophage infiltration, thus inhibiting tumor growth." (PMID 37361571, 2023). "While a few studies suggest that FUCA1 restrains tumor growth, attenuates cell motility, triggers cell death, and sensitizes cancer cells to chemotherapy, two other studies lead to quite opposite conclusions." (PMID 36864055, 2023). "AFU mediating defucosylation on these cells reduces their rolling ability and impairs the interaction between them and ECM, indicating the key role of FUCA1 in modulating tumor progression." (PMID 36046653, 2022). "HPA056371 is an antibody against FUCA1, which showed higher intensity in the normal tissue than in tumor tissue." (PMID 33692827, 2021). "The Kyoto Encyclopedia of Genes and Genomes (KEGG) analysis illustrated that FUCA1/FUCA2 exerted tumor-suppressive function by regulating the glycosylation." (PMID 34881177, 2021). "Downregulation of FUCA1 enhances autophagy and inhibits macrophage infiltration so as to inhibit tumor growth." (PMID 33692827, 2021). "In highly aggressive and metastatic human tumours, the FUCA-1 gene is downregulated, possibly because its inactivation disturbs the fucosylation of proteins involved in cell adhesion, migration and metastases." (PMID 31602256, 2019). "Well-differentiated tumor samples showed a higher number of positive cells for FUCA-1 compared to poorly differentiated tumors." (PMID 29632639, 2018). "A statistical analysis was further performed on the correlation between presence or absence of lymph-nodal metastases at diagnosis of the PTC, PDTC and ATC patients and expression levels of FUCA-1 in the tumor samples." (PMID 28404918, 2017). "Nearly 60% (n = 141) of the cases fell into Group 1 (tumor > normal, T > N); in this group, the mean FUCA1 expression level in the tumor samples was 148-fold greater than that in the normal samples (bars 3 vs. 4, *P = 0.001)." (PMID 26204487, 2015). "Our results indicate that higher FUCA1 expression (T > N) was positively correlated with nodal status and tumor stage (*P = 0.004 and *P = 0.004, respectively)." (PMID 26204487, 2015). "The average FUCA1 mRNA (copy number x 103/μg) expression was 139-fold higher in tumor tissue than in normal cells (bars 1 vs. 2, *P = 0.005, n = 236)." (PMID 26204487, 2015). "FUCA1 mRNA levels were examined in paired tumor and normal tissue samples by real-time RT-PCR analysis (n = 236)." (PMID 26204487, 2015). "We verified the expression level of FUCA1 in mouse tumour tissues using immunohistochemistry." (PMID 40487392, 2025). "This may include inhibition of FUTs to decrease fucosylation, or enhancement of FUCA1 activity, which has been speculated to possess tumor-suppressive potential." (PMID 39123480, 2024). "The results, taken together with the published observations, suggest that high FUCA-1 expression could decrease the abundance of fucose-containing glycans on the surface of cancer cells, and thereby attenuating tumor cell invasion." (PMID 28404918, 2017).
tumor (continued). "Two stable FUCA1 siRNA knock-down MDA-MB-231 cell lines were established, and the results suggest that transient FUCA inhibition creates a selective pressure that triggers the metastasis of primary tumor cells, as detected by wound healing and invasion assays (*P < 0.01)." (PMID 26204487, 2015). "However, in Group 2 (normal > tumor, N > T), the FUCA1 expression level in 72% (69/95) of the normal tissues was less than 20-fold greater than that in the tumor tissues (bars 5 vs. 6)." (PMID 26204487, 2015). "FUCA1 protein expression was determined by IHC staining of frozen tumor sections." (PMID 26204487, 2015). "To evaluate whether FUCA1 protein expression (FUCA H-score) in tumor tissue predicted overall survival, we used Cox regression proportional hazard analysis." (PMID 26204487, 2015). "Interestingly, FUCA1 was overexpressed at the mRNA and protein levels in cancer cells isolated from the original tumor sites (BT-474 and BT-483)." (PMID 26204487, 2015). "High FUCA1 expression in tumor tissue (T > N) was also associated with the non-smoking status in these patients (*P = 0.037)." (PMID 26204487, 2015). "Therefore, we hypothesized that the upregulation of FUCA1 promotes fucose-containing molecules to downregulate their expression on the surface of cancer cells, which can significantly inhibit tumor cell invasion." (PMID 30619732, 2018). "We have demonstrated that USP35 controls tumor growth and chemotherapeutic vulnerability in CRC by mediating the stability of FUCA1, indicating that USP35 is an intriguing target in CRC." (PMID 36864055, 2023). "During tumor progression, CAPZA1, GRB2, NF2EL3, PLEKHO1, SIGLEC1, and UBE2Z were expressed at higher levels in late-stage KIRC, whereas EMX2, FUCA1, IMPA2, and RORC were expressed at higher levels in early-stage KIRC." (PMID 35127943, 2022). "CAPZA1, HLA-E, IMPA2, NFE2L3, PLEKHO1, SIGLEC1, and UBE2Z were expressed at higher levels in tumor tissues, whereas EMX2, FGL2, FUCA1, and GRB2 were expressed at lower levels in tumor tissues." (PMID 35127943, 2022). "Our data demonstrated that tumor tissues contained significantly lower mRNA levels of FUT3 (2.3 fold), FUT4 (2.7 fold), FUT5 (5.9 fold), FUT6 (3.0 fold), FUT8 (2.0 fold), and FUCA1 (2.6 fold) as compared to adjacent normal tissues." (PMID 34703796, 2021). "Beyond that, we found significant correlations among FUCA1/FUCA2 expression and pathological grade, pathological stage, postoperative residual tumor numbers, and primary therapeutic effect." (PMID 34881177, 2021). "However, the role of FUCA-1 in tumor progression remains unclear." (PMID 28404918, 2017). "The results demonstrated that FUCA1 expression was negatively correlated with the proliferation, invasion, and migration abilities of MPM cells, suggesting that FUCA1 may have a tumor-suppressive role in MPM." (PMID 40487392, 2025). "Furthermore, the study suggests that the upregulation of FUCA1 expression contributes to the repression of the EGFR signaling pathway and has tumor‐suppressing activity in various human cancers." (PMID 37601653, 2023). "Given the enzymatic activity of USP35 and FUCA1, we provide an outlook that targeting USP35–FUCA1 axis could be a plausible strategy for restricting tumor growth and chemo-resistance in CRC." (PMID 36864055, 2023). "FGL2, FUCA1, PLEKHO1, and SIGLEC1 were highly expressed in DC and might influence its number in tumor." (PMID 35127943, 2022).
tumor (continued). "Within Group 1, higher FUCA1 expression (defined as > 100-fold) was detected in 58% (82/141) of the tumor tissue samples (data not shown)." (PMID 26204487, 2015). "FUCA1 mRNA levels were measured by RT-qPCR in paired tumor and normal mucosa tissues from 31 patients." (PMID 23965968, 2013). "The expression of FUCA-1 in BC patients with lymph node positive cancers, considering all molecular subtypes, was negative in 60% of patients against 40% being positive, thus suggesting that the lack of expression of FUCA-1 correlates with a more aggressive clinical behaviour of the tumor." (PMID 29632639, 2018).
cancer (16 papers, 2015 to 2025). A tumor composed of atypical neoplastic, often pleomorphic cells that invade other tissues. "High expression of FUCA1 was associated with the alteration of cell surface due to the fucosylation, which limits the invasiveness and metastasis of cancer cells in early stages." (PMID 29085821, 2017). "Interestingly, previous studies have connected FUCA1 deficiency to autophagic cell death in cancers, given the lysosomal enzyme nature of FUCA1." (PMID 36864055, 2023). "Down-regulation of FUCA1 has been consistently associated with cancer progression." (PMID 28404918, 2017). "Expression of FUCA1 decreases during TGFβ-induced EMT, resulting in the generation of highly fucosylated N-glycans associated with cancer development." (PMID 39123480, 2024). "FUCA1 mRNA expression is generally lower in cancer samples compared to normal counterparts, and this is associated with poor patient prognosis." (PMID 39123480, 2024). "On the other hand, the inconsistent effects of FUCA1 on cancer cell viability show that the mechanisms linking FUCA1 and cancer progression are as yet not fully understood." (PMID 39123480, 2024). "FUCA1 is an enzyme that hydrolyzes terminal fucose residues from glycolipids or glycoproteins, and its function in cancers remains obscure and controversial." (PMID 36864055, 2023). "Among these potential targets of USP35, we would like to specifically focus on α-L-fucosidase 1 (FUCA1) in our current study, considering the strong relevance of altered glycosylation in cancer development and therapeutics." (PMID 36864055, 2023). "In this study we have shown that FUCA-1 is able to define a subset of luminal B lymph node positive BC with longer cancer specific and overall survival." (PMID 29632639, 2018). "Cancer specific survival of luminal B LN+ patients was influenced by FUCA-1 expression as luminal B LN+ patients with positive expression had a longer cancer specific survival." (PMID 29632639, 2018). "As shown for other human cancers, the down-regulation of FUCA-1 correlates with increased aggressiveness of the cancer type." (PMID 28404918, 2017). "In contrast, FUCA1 protein expression was lower in cancer cells derived from metastatic sites (AU-565, MCF-7, MDA-MB-231, and MDA-MB-453)." (PMID 26204487, 2015). "In humans, the lysosomal degradation of fucosylated glycoconjugates depends on α-L-fucosidase activity, which is provided by the thoroughly characterized acidic tissue α-L-fucosidase (FUCA1) that is also involved in, for example, cancer progression and antigen processing." (PMID 40940767, 2025). "Therefore, we performed a series of functional studies under the regulation of USP35-FUCA1 axis, aiming to better understand the role of FUCA1 in cancers." (PMID 36864055, 2023). "Based on current findings of FUCA1, the role of FUCA1 in cancers still remains controversial." (PMID 36864055, 2023).
cancer (continued). "According to various studies, it appears that the expression of FUCA1 in human cancers is complex." (PMID 37601653, 2023). "FUCA-1 mRNA expression was inversely related to cancer stage and lymph node involvement." (PMID 29632639, 2018). "Moreover, cancer specific survival of luminal B LN+ patients was influenced by FUCA-1 expression, since these patients, having positive FUCA-1 expression, had a longer survival." (PMID 29632639, 2018). "FUCA1 is an important protein involved in cancer progression." (PMID 29085821, 2017). "We further explored the function of FUCA1 in human cancer cell lines." (PMID 26204487, 2015). "Targeting FUCA1 could potentially inhibit cancer progression and improve patient prognosis." (PMID 40487392, 2025). "Notably, FUT11, BGLAP, SSR2, TGFBR1, BSG, and FUCA1 have been reported to be associated with related cancer, but no studies showed the functions of other eight DESPGs in corresponding cancers." (PMID 31824949, 2019). "Considering the previously reported role of FUCA1 in cancer growth and chemo-resistance, we here investigated whether the influence of USP35 on cell proliferation and drug resistance was mediated or partially mediated by FUCA1 in our study." (PMID 36864055, 2023). "In addition, proteins that have been related to other cancers but not to BC yet, were also identified, such as fibulin-2 (FBLN2), tissue alpha-L-fucosidase (FUCA1), staphylococcal nuclease domain-containing protein 1 (SND1), and EIF3D." (PMID 29050215, 2017).
FUCA1 also shares sentences with these, for which no sentence is quoted: hepatocellular carcinoma (4 papers); glioblastoma (2); anaplastic carcinomas (1); colon adenocarcinoma (1); dysostosis (1); endometrial carcinoma (1); epilepsy (1); Fabry disease (1); frontotemporal dementia (1); gastric cancer (1); Gaucher disease (1); Hepatic steatosis (1); Intellectual disability (1); Kidney (1); Krabbe disease (1); Lipid storage disease (1); liver cancer (1); lymph node metastasis (1); malignant pleural mesothelioma (1); metabolic syndrome (1); neuronal ceroid lipofuscinosis (1); Parkinsonism (1); prostate carcinoma (1); Sepsis (1); Tay-Sachs disease (1); thyroid tumor (1); Urethral stricture (1).